CTAGE1 (cutaneous T cell lymphoma-associated antigen 1)
Synonyms: CT21.1; CT21.2; cTAGE-1; cTAGE-2; CTAGE
Tractability: Antibody: UniProt predicts a signal peptide or a membrane-spanning region. PROTAC: ubiquitination databases record sites on it.
Gene: Protein-coding gene on chromosome 18 (22,413,599 to 22,417,915, reverse strand). Ensembl gene ENSG00000212710.
Subcellular location: Membrane
Gene Ontology:
Biological process: endoplasmic reticulum to Golgi vesicle-mediated transport; protein secretion; vesicle cargo loading
Cellular component: endoplasmic reticulum exit site; endoplasmic reticulum membrane; membrane
Genetic constraint (gnomAD): Missense variants: 963 observed, 885.96 expected, observed/expected ratio (o/e) 1.09, 90% interval 1.03 to 1.15. Synonymous variants: 332 observed, 312.98 expected, observed/expected ratio (o/e) 1.06, 90% interval 0.97 to 1.16.
Homologues: Orthologues: chimpanzee CTAGE1 (97% identical), dog MIA2 (81% identical), rat Mia2 (72% identical), mouse Mia2 (72% identical), Drosophila melanogaster Tango1 (22% identical). Paralogues in human: MIA2 (88% identical), CTAGE15 (78% identical), CTAGE8 (78% identical), CTAGE9 (78% identical), CTAGE6 (78% identical), CTAGE4 (78% identical), MIA3 (27% identical), SPZ1 (10% identical), MIA (2% identical), OTOR (2% identical).
Diseases named in the same sentence as CTAGE1 in open-access papers:
CTAGE1 is named in the same sentence as 14 diseases in open-access papers, as found by Europe PMC text mining. Sharing a sentence is not in itself a finding about the gene and the disease. The quoted sentences say what the papers report.
colorectal cancer (1 paper, 2017). A primary or metastatic malignant neoplasm that affects the colon or rectum. "CTAGE1 antibodies were also found in sera of colorectal cancer patients." (PMID 29190970, 2017).
T-cell lymphoma (1 paper, 2019). "The gene CTAGE1 is described as a cancer antigen for T-cell lymphoma and other malignancies, and is expressed in 12–19% CRCs." (PMID 30952955, 2019).
CTAGE1 also shares sentences with these, for which no sentence is quoted: cancer (6 papers); aortic stenosis (1); blood cancer (1); chronic fatigue syndrome (1); cutaneous T-cell lymphoma (1); generalized epilepsy (1); male infertility (1); panic disorder (1); personality disorder (1); Pseudoxanthoma elasticum (1); Sezary syndrome (1); tumour (1).